NEAT1 (nuclear paraspeckle assembly transcript 1)
Diseases named in the same sentence as NEAT1 in open-access papers (continued):
Sharing a sentence is not in itself a finding about the gene and the disease.
multiple myeloma (continued). "As anticipated, knockdown of NEAT1 results in a downregulation of DNA-repair processes and re-sensitizes multiple myeloma cells to common chemotherapeutic agents." (PMID 32266130, 2020). "Recent data showed that NEAT1 can inhibit apoptosis in multiple myeloma cells by regulating genes involved in DNA-repair processes, including the homologous-recombination pathway, suggesting its association with drug resistance." (PMID 32819367, 2020). "The data we present hereby provide the foundation for studying the effect(s) of lncRNA Neat1 and paraspeckles on blood cancer, including Leukemia, Myeloma or Lymphoma." (PMID 29312630, 2017). "Most interestingly, a recent study revealed Neat1 dysregulation in Multiple Myeloma, pioneering its clinical hematological relevance." (PMID 29312630, 2017). "Exosomal NEAT1 has been established as an oncogene in OC and multiple myeloma." (PMID 40410719, 2025). "In human myeloma cell lines (HMCLs), they found NEAT1 silencing treatment increased anti-multiple myeloma drugs sensitivity, which indicated that a combination of NEAT1 silencing with Olaparib, bortezomib, carfilzomib, and melphalan showed a synergistic effect." (PMID 38356722, 2024). "Therefore, Exosomal lncRNA NEAT1 is up-regulated in multiple myeloma, and NEAT1 represses PBX1 by recruiting EZH2." (PMID 39346921, 2024). "Besides, NEAT1 accelerates multiple myeloma progression by regulating B7-H3 to promote M2 macrophage polarization." (PMID 36941678, 2023). "NEAT1 can regulate gene transcription in key processes, including DNA repair and the cell cycle, and in this study, NEAT1 knockdown led to a reduction in the proliferation of in vitro myeloma cell lines." (PMID 37511018, 2023). "The findings showed that the lncRNA NEAT1 was highly expressed in multiple myeloma cells and that resveratrol could effectively inhibit it." (PMID 35566016, 2022). "For instance, lncRNA NEAT1 leads to DNA damage in multiple myeloma." (PMID 35173610, 2021). "A study found that lncRNA NEAT1 could be used as a biomarker of multiple myeloma, and myeloma cells could inhibit the differentiation of BMSCs into osteoblasts." (PMID 34595348, 2021). "NEAT1 promoted cell proliferation in multiple myeloma by activating PI3K/Akt pathway." (PMID 32268876, 2020). "In multiple myeloma, NEAT1 forms a positive feedback loop with SP1, in which NEAT1 induces SP1 expression by sequestering hsa-miR-29b-3p, and SP1 targets NEAT1 promoter region inducing NEAT1 transcription, and collectively promoting tumor cell survival." (PMID 35008626, 2021). "Furthermore, we demonstrated that the NEAT1 KD effect in HMCLs is synergic with proteasome inhibitors (bortezomib and carfilzomib) or alkylating agent (melphalan) treatments, indicating that NEAT1 silencing triggers a general sensitizing effect to anti-MM (multiple myeloma) drugs." (PMID 32630183, 2020). "It was found that the expression of NEAT1 is significantly higher in multiple myeloma patients compared to controls and does not change with other clinical features and cytogenetic features." (PMID 37407915, 2023). "In summary, we have shown that the expression of NEAT1 in PBMC is independent of age, gender, disease stage, BM PC percentage, myeloma protein and cytogenetic factors, suggesting that lncRNA in peripheral blood can be used as a diagnostic test for myeloma." (PMID 37407915, 2023).
nasopharyngeal carcinoma (35 papers, 2017 to 2025). A carcinoma arising from the nasopharyngeal epithelium. "The combination of NEAT1 normalization and radiation therapy may represent a novel and promising therapeutic method within a subset of NEAT1-deficient patients with nasopharyngeal carcinoma." (PMID 29050268, 2017). "NEAT1 is a highly conserved single exon, intergenic lncRNA frequently upregulated in numerous cancers, including nasopharyngeal carcinoma, esophageal squamous cell carcinoma, and NSCLC, et cetera." (PMID 38472205, 2024). "In nasopharyngeal carcinoma NEAT1 targets hsa-miR-34a-5p which in turn activates Wnt/β-catenin signaling promoting tumor cell proliferation, migration, invasion, and EMT." (PMID 35008626, 2021). "Supplementing camptothecin to MCF‐7 cells supported further our findings, suggesting that NEAT1 affects cell proliferation and apoptosis in context of miR‐204, and pointing to a reciprocal repression feedback loop in BC as observed in nasopharyngeal carcinoma." (PMID 30803129, 2019). "In nasopharyngeal carcinoma, NEAT1 enhanced the cisplatin resistance by targeting Rsf-1 and Ras-mitogen-associated protein kinase signaling pathway." (PMID 30894512, 2019). "In the current study, cDNA microarray analysis found that NEAT1 expression was reduced in nasopharyngeal carcinoma (NPC) patients and that it regulated NPC progression." (PMID 29050268, 2017). "We consider NEAT1 to be highly involved in the modulation of irradiation resistance and metastatic recurrence in nasopharyngeal carcinoma." (PMID 29050268, 2017). "NEAT1/miR-124-3p/p65 (NF-κB) axis induces NF-κB signaling pathway in nasopharyngeal carcinoma." (PMID 36362406, 2022). "In nasopharyngeal carcinoma, highly expressed lncRNA NEAT1 could accelerate tumor growth through suppressing mIR-124 via NF-κB signaling pathway." (PMID 33023572, 2020). "Furthermore, upregulation of NEAT1 promoted the development and progression of nasopharyngeal carcinoma by regulating the miR-124/NF-κB signaling pathway." (PMID 33817255, 2020). "Besides, NEAT1 sponged miR-124 in neuroblastoma, retinoblastoma, Alzheimer’s disease and nasopharyngeal carcinoma." (PMID 31868202, 2020). "In conclusion, the current study provides some novel insights into a ceRNA mechanism of NEAT1 regulation in the metastasis and radiation resistance of nasopharyngeal carcinoma and identifies NEAT1 as a novel prognostic biomarker for metastasis risk and radiation sensitivity." (PMID 29050268, 2017). "We hope that NEAT1-targeted therapeutics might be developed as a potential therapeutic strategy, alone or combined with irradiation, for the diagnosis and treatment of nasopharyngeal carcinoma." (PMID 29050268, 2017). "Recent research could draw connections between NEAT1 and nasopharyngeal carcinoma (NPC)." (PMID 30430751, 2019). "Furthermore, the axis of NEAT1/miR-204-5p/ZEB1 was confirmed in nasopharyngeal carcinoma." (PMID 29285225, 2017). "LncRNAs like MALAT1 and NEAT1 contribute to radioresistance, with MALAT1 modulating resistance in nasopharyngeal cancer via miR-1 inactivation and NEAT1 promoting resistance through the miR-204/ZEB1 axis." (PMID 40150019, 2025). "The lncRNA nuclear enriched abundant transcript 1 (NEAT1) can affect EMP2 expression via miR-101-3p and slow the progression of nasopharyngeal carcinoma." (PMID 36217151, 2022). "Let-7a-5p overexpression knocked down NEAT1, resulting in MAPK pathway inhibition and suppressing tumor growth in nasopharyngeal carcinomas if cisplatin treatment was ongoing." (PMID 34769348, 2021). "On the other hand, as ZEB1 was identified as a downstream target of miR-205, the expression level of miR-205 can be inhibited by nuclear enriched abundant transcript 1 (NEAT1), which regulates EMT progress and radioresistance in nasopharyngeal carcinoma." (PMID 32014049, 2020).
nasopharyngeal carcinoma (continued). "A physical interaction was also reported between nuclear paraspeckle assembly transcript 1 (NEAT1) and miR‐204, forming a reciprocal repression feedback loop in nasopharyngeal carcinoma." (PMID 30803129, 2019). "Tumor suppressor miR-124 could be interacted with NEAT1 and down-regulated in nasopharyngeal carcinoma (NPC) cells, elevated NEAT1 level in tumor tissues promoted the cell growth and the progression of NPC through regulating miR-124/NF-κB signaling pathway." (PMID 29654165, 2018).
colon carcinoma (33 papers, 2016 to 2026). "This investigation connected NEAT1 gene variants to the spread of colon cancer; however, additional efforts are necessary to deal with several study limitations." (PMID 41323778, 2025). "Furthermore, rs3825071 may be involved in the regulation of NEAT1 gene expression, which is associated with the survival in colon cancer patients of the younger age group." (PMID 41323778, 2025). "Nuclear enriched abundant transcript 1 (Neat1), a long non-coding RNA (LncRNA), exerts a cancer-promoting effect in some tumors, such as thyroid carcinoma, colon cancer, liver cancer, and melanoma." (PMID 36335386, 2022). "In contrast, NEAT1 was reported to induce autophagy to enhance drug resistance of colon cancer and HCC." (PMID 35054896, 2022). "In colon cancer, for example, high levels of NEAT1 correlate with enhanced growth and proliferation, as well as poor prognosis for disease-free survival." (PMID 35457249, 2022). "The demethylation of the lncRNA NEAT1 caused by ALKBH5, an m6A demethylase, promotes the progression of colon cancer." (PMID 35912098, 2022). "NEAT1 triggered cell proliferation and migration in colon cancer by inhibiting miR-185-5p and elevating IGF2." (PMID 33902591, 2021). "Based on this assumption, we provide the first evidence that plant mtr-miR5754 and gma-miR4995 can significantly reduce the level of MALAT1 and NEAT1 in colon cancer cell lines." (PMID 33193626, 2020). "NEAT1 was also shown to promote colon cancer progression via up-regulating CDK6 by sponging miR-495-3p." (PMID 33336058, 2020). "In colon cancer, NEAT1 activates Wnt/β-catenin signaling, promoting cancer progression." (PMID 35804870, 2022). "ALKBH5 promotes colon cancer progression by decreasing methylation of the NEAT1." (PMID 36032659, 2022). "LncRNA NEAT1 has been verified to participate in colon cancer development and progression." (PMID 35676702, 2022). "In summary, our work demonstrated that NEAT1 was associated with 5-Fu resistance in CRC patients, suggesting that NEAT1 may affect 5-Fu resistance in colon cancer cells by affecting cancer cell stem." (PMID 33168814, 2020). "Moreover, it is striking that rs3825071 was merely linked to metastatic potentials of colon cancer whereas not to that of rectal cancer, indicating an anatomical site-specific influence of NEAT1 gene variations on the spread of colorectal neoplasms." (PMID 41323778, 2025). "The expression of LncRNA NEAT1 is closely related to the overall survival of colon cancer patients, and overexpression of NEAT1 can significantly promote the migration and invasion of colon cancer cells by competitively and endogenously binding to miR-185-5p to regulate IGF2." (PMID 38002356, 2023). "Moreover, ALKBH5 or NEAT1 gene knockout can partially inhibit the malignant behavior of colon cancer; CircNSUN2 is often upregulated in patients with liver metastasis (LM) from colorectal cancer and is exported from nucleus to cytoplasm in an m6A-dependent manner through binding to YTHDC1." (PMID 35070987, 2021). "The Nuclear paraspeckle assembly transcript 1 (NEAT1) lncRNA, located on chromosome 11q13.7, was originally investigated by Sayad and colleagues for its regulatory role in apoptosis in colon cancer." (PMID 40723809, 2025). "In colon cancer, ALKBH5 can up-regulate the expression of lncRNA NEAT1 through demethylation modification, thereby promoting tumor progression." (PMID 35070987, 2021). "The authors tested chitosan-based NPs loaded with lncRNA NEAT1 siRNA on human HCT-116, Lovo and SW480 colon cancer cells, as well as a normal NCM460 colonic cell line, observing an important growth inhibition in all the colon cancer cells." (PMID 35457155, 2022). "Overexpressed NEAT1 via the miR-185-5p/IGF-2 axis could promote invasion and migration of colon cancer cells." (PMID 33768092, 2021).
colon carcinoma (continued). "Moreover, the NEAT1/miR-185-5p/insulin-like growth factor 2 (IGF2) axis is another pathway that induces the invasion and migration of colon cancer." (PMID 34512157, 2021). "In addition, NEAT1 increased the level of histone acetylation, and the heightened histone enrichment at the ALDH1 and c-Myc promoters led to the upregulation of ALDH1 and c-Myc expression, thereby impacting 5-Fu resistance in colon cancer cells through modulation of cancer cell stemness." (PMID 39830506, 2024).
Parkinson disease (30 papers, 2015 to 2025). A progressive degenerative disorder of the central nervous system characterized by loss of dopamine producing neurons in the substantia nigra and the presence of Lewy bodies in the substantia nigra and locus coeruleus. "NEAT1 is important for neural development and functioning and has been associated with psychiatric diseases including Alzheimer’s, Huntington’s, and Parkinson’s disease." (PMID 38374201, 2024). "Increased NEAT1 is associated with several cognitive and neurodegenerative disorders such as AD, schizophrenia, Huntington's, and Parkinson's." (PMID 34621163, 2021). "Furthermore, NEAT1 is associated with the modulation of autophagy in diseases such as congenital heart disease, Parkinson’s disease and myocardial ischemia-reperfusion injury." (PMID 39715205, 2024). "As such, NEAT1 aggravates autophagy and cell injury in the MPTP-induced Parkinson's disease model, whereas downregulation of NEAT1 inhibits Aβ uptake and degradation by regulating endocytosis-related gene expression in Alzheimer's disease." (PMID 38212456, 2024). "Elevated Neat1 levels were also detected in postmortem brain samples and the peripheral blood of patients with Parkinson’s disease." (PMID 37614230, 2023). "NEAT1 is highly expressed in the brain of AD patients, playing pathological effects in other neurodegenerative diseases such as Huntington’s and Parkinson’s diseases." (PMID 36947499, 2023). "Several studies have reported upregulation of NEAT1 in cellular and mouse models of Parkinson’s disease as well as in the PB and SN of PD patients." (PMID 35796900, 2022). "For example: In Parkinson’s disease, lncRNA NEAT1 increases stabilization of PTEN-induced putative kinase 1 (PINK1), hence promoting cellular quality control mechanism." (PMID 35359568, 2022). "NEAT1 is elevated in peripheral blood cells of Parkinson’s disease patients and abnormally expressed in a wide variety of human cancers." (PMID 36552736, 2022). "Conversely, Simchovitz A suggested that NEAT1 may serve a protective role in Parkinson’s disease, via the depletion of NEAT1-induced cell death after paraquat-induced oxidative stress." (PMID 40362651, 2025). "Given that ACSL4 and GPX4 are pivotal regulators of ferroptosis, lncRNA NEAT1 might modulate ferroptosis via these molecules, presenting a promising therapeutic approach for Parkinson’s disease." (PMID 39280701, 2024). "Knockdown of lncRNA NEAT1 downregulated Cx32 expression via the promotion of miR-1301-3p, a suppressor of Gjb1 (Cx32); suppressed the α-synuclein-induced inflammatory response; and reduced apoptosis in a cellular Parkinson’s disease (PD) model." (PMID 38892334, 2024). "Although the precise role of NEAT1 in neurodegeneration remains elusive, its abnormal expression has been associated with various conditions, including amyotrophic lateral sclerosis (ALS), Alzheimer’s, Parkinson’s, and Huntington’s disease." (PMID 38125008, 2023). "NEAT1 regulation of the miR-212-3p/AXIN1 pathway might be a therapeutic target for neuroprotection in Parkinson’s Disease." (PMID 36523600, 2022). "Furthermore, the expression profiles of the lncRNAs Malat1, Neat1, and Gas5 were significantly dysregulated in the Parkinson's disease model, with Malat1 and Neat1 showing notable upregulation, which has been associated with enhanced oxidative stress and neuroinflammation." (PMID 41208834, 2025). "While no function is known for most of these non-coding RNAs, the upregulation of lncRNA of NEAT1 (2.2-fold, q-value 3.7 × 10−5) is intriguing, as NEAT1 was proposed to be upregulated in response to oxidative stress and as a potential biomarker in Parkinson’s diseases." (PMID 39062793, 2024). "However, a neuroprotective role for NEAT1 is proposed in Parkinson's disease (PD)." (PMID 32970857, 2021).
Parkinson disease (continued). "Interestingly, the level of NEAT1 increases in the peripheral blood of patients with Parkinson’s disease compared to non-affected patients and could reflect the overexpression of NEAT1 in the sustancia nigra of patients with Parkinson’s disease." (PMID 38374201, 2024). "Neat1 activated the NLRP3 inflammasome and upregulated proinflammatory cytokines by sponging several microRNAs in Parkinson’s disease." (PMID 37614230, 2023). "Additionally, lncRNA NEAT1 impacts Parkinson’s disease pathology by sponging miR-212-3p, which targets AXIN1, while lncRNA SNHG1 exacerbates neuroinflammation in Parkinson’s disease through the miR-7/NLRP3 pathway." (PMID 39280701, 2024).